TMPRSS2 (transmembrane serine protease 2)
Diseases named in the same sentence as TMPRSS2 in open-access papers (continued):
Sharing a sentence is not in itself a finding about the gene and the disease.
infection (continued). "While infection efficiencies were somewhat variable, the results clearly showed that N322A and lack of all N-linked glycosylation sites in ACE2 only increased infection in the absence but not in the presence of TMPRSS2." (PMID 40152594, 2025). "Genetic investigations show that African populations have low TMPRSS2 expression levels, which might decrease their vulnerability to infection." (PMID 40297833, 2025). "While age-dependent variations in ACE2, TMPRSS2, and FURIN expression may influence infection susceptibility and disease manifestation, current evidence remains inconclusive." (PMID 40370452, 2025). "The expression levels of TMPRSS2 and ISGs in the CNS may determine the level of infection and thus affect the vulnerability of individuals with DS to neurological complications." (PMID 40445428, 2025). "This may also be an explanation for why the neurosensorial phenotype is less common after infection with postancestral SARS‐CoV‐2 variants, as mutations in these variants reduce their efficiency in infecting TMPRSS2‐expressing host cells." (PMID 40492581, 2025). "However, the contribution of cathepsins was as significant as or more significant than TMPRSS2 in BA.1 infection of these organoids." (PMID 39601592, 2025). "Thus, even after recovery of TMPRSS2 availability, the cathepsin-mediated pathway was still important for infection of these Omicron subvariants." (PMID 39601592, 2025). "Notably, AAT cells express both human ACE2 and TMPRSS2 ectopically and as such are permissive for infection by both entry routes." (PMID 39753670, 2025). "In addition to the OAS1 region, CapAeg_1.233:ERVK:LTR (chr1:141284178-141285910) proximal to another important immune gene, TMPRSS2, was altered during endometrium development and under infection." (PMID 40176799, 2025). "This dual role positions TMPRSS2 as a potential molecular bridge linking infection and oncogenesis." (PMID 41267989, 2025). "Moreover, it has been demonstrated that infection of SARS-CoV-2 in mature enterocytes expressing ACE2 is facilitated by TMPRSS2, highlighting the intestine as a potential site of SARS-CoV-2 replication." (PMID 41007801, 2025). "It has been previously suggested that blocking TMPRSS2-mediated entry may promote the use of the cathepsin-driven endosomal pathway and potentially increase total infection." (PMID 40152594, 2025). "ACE2 and TMPRSS2 are both known to be highly expressed in the thyroid as in the lungs, so direct infection of a virus into thyroid follicular cells could occur." (PMID 39882352, 2025). "However, mostly non-cleaved precursor S0 was present when the cells were treated with MI-1851, again highlighting that TMPRSS2 cannot compensate for furin during authentic infection in human airway cells." (PMID 39599912, 2024). "Interestingly, TMPRSS2 knockout mice exhibit reduced pathogenesis upon infection with SARS-CoV, MERS-CoV and SARS-CoV-2, emphasizing the protease’s pivotal role in CoV activation and pathogenesis." (PMID 39599912, 2024). "Similar to ACE2 levels, TMPRSS2 expression levels before infection were different between symptomatic and asymptomatic patients, where symptomatic patients showed high TMPRSS2 expression levels pre-infection." (PMID 38606293, 2024). "Even with an already robust understanding of the influence of ACE2 and TMPRSS2 on infections via the new coronavirus, when the additional variable of several SARS-CoV-2 variants is added to the equation, a new and complex set of yet-to-be-studied associations arises." (PMID 39597701, 2024). "Other proteinases that facilitate virus entry, such as alanyl-aminopeptidase (ANPEP), glutamyl aminopeptidase (ENPEP), and transmembrane serine protease 2 (TMPRSS2), may also aid in the infection of lung cells." (PMID 39591123, 2024).
infection (continued). "Mechanistically, the proximity of this epitope to the S2’ cleavage site raises the possibility that such antibodies could neutralize SARS-CoV-2 by inhibiting S2’ cleavage by TMPRSS2, an event that is necessary for host cell infection." (PMID 38189279, 2024). "Although direct infection of SARS-CoV-2 of ECs has been described, findings regarding the susceptibility of ECs for infection and the expression of the receptor angiotensin-converting enzyme 2 (ACE2) and transmembrane protease serine 2 (TMPRSS2) are controversial." (PMID 39739157, 2024). "Infection can be significantly enhanced in Vero E6 cells transfected with human TMPRSS2." (PMID 39337465, 2024). "Infection of cells with Omicron was shown to occur via the endocytic pathway rather than direct fusion on the plasma membrane, and was therefore less dependent on TMPRSS2 expression in the cells." (PMID 38500504, 2024). "Canonically, TMPRSS2 is the protease responsible for infection within the lungs yet SARS-CoV-2 has been found in tissues that do not express TMPRSS2 leading to the discovery of secondary proteases involved in the S1/S2 cleavage within cells as opposed to the surface fusion TMPRSS2 is involved in." (PMID 38793666, 2024). "ACE-2 and TMPRSS2 are well-established viral receptors that aid in viral entry and infection." (PMID 39066223, 2024). "Inhibiting the activity of TMPRSS2 can block the infection of lung cells by SARS-CoV-2." (PMID 39195243, 2024). "In addition, TMPRSS2-enhanced infections increased rates of cytopathology, apoptosis, and necrosis and modulated virus secretion kinetics in a variant-specific manner." (PMID 38814864, 2024). "Although many proteases have been documented to proteolytically process HA with monobasic cleavage sites upon co-expression in vitro, we previously showed that TMPRSS2 is the major activating protease for most IAV subtypes during infection of Calu-3 human airway cells." (PMID 39599912, 2024). "For example, TMPRSS2 also facilitates infection of the respiratory epithelium by the influenza A virus, and AAT may inhibit this effect, although the mechanism remains unknown." (PMID 38339082, 2024). "The results showed that the cells were susceptible to virus infection, and the infection mechanism was independent of the ACE2/TMPRSS2 system." (PMID 39273582, 2024). "In addition, symptomatic patients presented higher expression levels of TMPRSS2 pre-infection, which decreased in the following periods." (PMID 38606293, 2024). "However, the addition of camostat mesylate (an inhibitor of serine transmembrane proteases including TMPRSS2) alone or in combination with E64d strongly blocked infection of WA1 and Delta in nasal ALI." (PMID 38291024, 2024). "Additionally, in A549 cells engineered to express ACE2 and TMPRSS2, Omicron exhibited reduced infection capacity compared to Delta." (PMID 38560455, 2024). "We hypothesized that quercetin could inhibit entry of the virus into cells, either directly or via regulation of ACE2 and TMPRSS2 expression, thereby impeding the infection, increasing viral clearance and limiting COVID‐19 progression." (PMID 38886986, 2024). "Inhibitors of TMPRSS2, such as the serine protease inhibitor camostat mesylate (Ono Pharmaceutical, Osaka, Japan), have been demonstrated to impede the activity of TMPRSS2, thereby blocking the infection of lung cells by SARS-CoV-2." (PMID 39195243, 2024). "In asymptomatic patients, an increase in TMPRSS2 levels was observed during infection, which could indicate a possible viral modulation of the protease, hence increasing its expression to facilitate viral dissemination." (PMID 38606293, 2024). "As Omicron uses a different TMPRSS2-independent infection pathway, this may indicate that TMPRSS2 is involved in the LPS-mediated effect, but this would require direct testing in future work." (PMID 38862017, 2024). "Thus, cells with high ACE2 and TMPRSS2 expression have strong virus-binding ability and are particularly prone to infection." (PMID 38541618, 2024).
infection (continued). "The reduction in TMPRSS2 expression post-infection complements this hypothesis by showing that in the absence of SARS-CoV-2, the expression levels are restored to those observed during the pre-infection period." (PMID 38606293, 2024). "In all these studies, the arginine residues play a catalytic role in the basic cleavage sites (R685–S686 and R815–S816) for the S-protein’s cleavage and therefore trigger infection induced by proteases, such as furin and transmembrane serine protease 2 (TMPRSS2)." (PMID 37368467, 2023). "The SARS-CoV-2 virus uses TMPRSS2 as a host for S protein priming and fusion of viral and host cell membranes, which could explain why there is a higher infection burden amongst Black people." (PMID 36895058, 2023). "Infection experiments performed in the presence of different concentrations of nafamostat mesylate with normal PK-15 and PK-15/TMPRSS2 #23 cells showed that nafamostat mesylate inhibited viral replication in PK-15/TMPRSS2 #23 cells." (PMID 38251326, 2023). "Importantly, amuvatinib inhibited ACE- and TMPRSS2-mediated SARS-CoV-2pp infection in a dose-dependent manner." (PMID 36995225, 2023). "More stable RBD-ACE2 association is coupled with accelerated hydrolysis by proteases, such as furin, trypsin, and the Transmembrane Serine Protease 2 (TMPRSS2) that augment infection rates, while inhibition of the 3-chymotrypsin-like protease (3CLpro) can prevent the viral replication." (PMID 36851526, 2023). "Taken together, our results, in hand with other studies, highlight the importance of ACE2 in the cell entry of SARS-CoV-2, whereas, in contrast to previous reports, the priming protease TMPRSS2 was found as dispensable in the infection of cultured AB8 podocytes." (PMID 36979408, 2023). "Pantethine treatment inhibited the infection-induced increase in TMPRSS2 expression in Calu-3a cells, suggesting that pantethine may affect SARS-CoV-2 entry by reducing the expression of TMPRSS2." (PMID 36754974, 2023). "The infection process is facilitated by the transmembrane protease serine 2 (TMPRSS2)." (PMID 37626735, 2023). "Importantly, cells differentiated from hESCs can become susceptible to the infection, especially if the daughter cells express high levels of ACE2 and TMPRSS2." (PMID 36453030, 2023). "Cells expressing both ACE2 and TMPRSS2 are highly permissive to infection." (PMID 37288969, 2023). "Interestingly, only a trend of Tmprss2 downregulation was observed in the lungs of infected C57BL/6J mice, which is the least susceptible mouse strain to MA10 infection." (PMID 36728430, 2023). "SARS-CoV-2 may not bind to target cells if its expression is suppressed, but tissue (co-) expression of ACE2 and TMPRSS2 near viral entry sites may increase infection." (PMID 37371774, 2023). "Infection was performed in Huh-7 cells expressing the transmembrane serine protease 2 (TMPRSS2)." (PMID 37298740, 2023). "Permissiveness to infection seems not to be associated with the expression of TMPRSS2, as highly permissive HepG2 and Huh7.5ACE2 cell lines demonstrated strong heterogeneity in the expression of this gene." (PMID 36765590, 2023). "Under this condition, a residual level of infection was maintained that might result from the involvement of some other proteases or even TMPRSS2-6xD itself." (PMID 37896901, 2023). "Thus, Calu-3 cells, which express AR and TMPRSS-2 and thereby mimic natural infection, were used for further experiments." (PMID 36834705, 2023). "In summary, more efficient use of TMPRSS2-dependent infection by BA.5 and XBB (and original ancestral isolates) compared to BA.1, may promote entry into the brain of K18-hACE2 mice via the olfactory epithelium." (PMID 38075874, 2023). "This has raised concerns about the potential impact of SARS-CoV-2 infection on organs with high ACE2 or TMPRSS2 expression that may be more vulnerable to adverse sequelae due to infection." (PMID 37867530, 2023).
infection (continued). "Infection of Omicron Y655H mutant was TMPRSS2 responsive and E64d irresponsive." (PMID 37243215, 2023). "Furin, together with TMPRSS2 (transmembrane protease serine 2), is responsible for the cleavage of the SARS-CoV-2 S protein, which represents the SARS-CoV-2 co-receptor, regulates its entry into host cells, and is related to an enhanced risk of infection." (PMID 36675784, 2023). "The infection of mice with the Omicron variant did not cause disease, as expected, but again, TMPRSS2 was essential for efficient viral spread in the upper and lower respiratory tract." (PMID 36851486, 2023). "After the ACE2 binding, transmembrane protease serine 2 (TMPRSS2), a host protease which is essential for Spike protein priming, has been shown playing important a role in virus-host cell membrane fusion and further infection." (PMID 38089696, 2023). "Furthermore, OM-ALI cells expressed genes for all the characteristic proteins that are important for viral entry and infection, such as TMPRSS-2, CTSB, CTSL, NRP-1, BSG, and furin." (PMID 38098019, 2023). "It is plausible that steroid receptors, aside from modulating the immune system, might also influence the expression of ACE2 and TMPRSS2, potentially impacting the uptake and infection of SARS-CoV-2." (PMID 37809955, 2023). "However, addition of camostat mesylate (an inhibitor of serine transmembrane proteases including TMPRSS2) alone or in combination with E64d strongly blocked infection of WA1 and Delta in nasal ALI." (PMID 37425811, 2023). "In addition, pantethine inhibited the infection-induced increase in TMPRSS2 and HECT E3 ligase expression in infected cells as well as the increase in antiviral interferon-beta response and inflammatory gene expression in Calu-3a cells." (PMID 36754974, 2023). "TMPRSS2 knockout or inhibition reduces infection in mouse models of SARS and MERS." (PMID 35294338, 2022). "Thus, ATD does not appear to be a suitable option for prevention and treatment of infection with TMPRSS2-dependent viruses." (PMID 35163273, 2022). "HEK293T do not express TMPRSS2 and cells ectopically expressing TMPRSS2 were more susceptible to infection with both SARS-CoV-2 and the related pseudovirions." (PMID 35388061, 2022). "Severe acute respiratory syndrome coronavirus-2 (SARS-CoV-2) begins its infection through the priming of spike (S) protein by transmembrane protease serine 2 (TMPRSS2) on the host cell membrane and interaction of S protein with angiotensin-converting enzyme 2 (ACE2) receptors." (PMID 35027080, 2022). "TMPRSS2 expression is relatively higher than ACE2 expression in the trachea where potential infection may occur." (PMID 35255100, 2022). "Also, initial treatment with dexamethasone and euthyroid cells results in downregulation of ACE-2 and TMPRSS2 in RBCs and decreases infection with the virus." (PMID 35872770, 2022). "In addition, in vitro studies are needed to evaluate the presence of ACE2 and TMPRSS2 in human musculoskeletal tissues because this seems to be necessary for the infection and related tissue damage." (PMID 35911401, 2022). "The BtKY72 chimeric virus exhibited slightly increased infection in the presence of TMPRSS2." (PMID 35895696, 2022). "However, to the best of our knowledge, we are the first to report that enoxaparin significantly augmented AAT inhibition of TMPRSS2 activity and an in vitro infection with a human coronavirus." (PMID 35338216, 2022). "Alternatively, ceramide-enriched membrane domains might trap ACE2 and TMPRSS2 within a small, distinct area of the plasma membrane resulting in a high concentration of TMPRSS2 and thereby S-protein priming, membrane fusion and infection." (PMID 34608263, 2022). "Activation of VSV-SARS-CoV-2-Atto 565 by brief treatment with trypsin for 30 minutes followed by the addition of the trypsin inhibitor aprotinin bypassed the requirement for host cell proteases TMPRSS2 and cathepsin L for infection--implicating that trypsin treatment cleaved the S2’ site." (PMID 35951767, 2022).
infection (continued). "Noteworthy, the triple staining data, in combination with previous single and double staining data, suggests that the virus does not necessarily require significant expression of both ACE2 and TMPRSS2 to mediate infection, as seen in the left, accessory, and right upper/mid lobe." (PMID 35255100, 2022). "With the reduced sensitivity to furin and TMPRSS2 cleavage, the rVSV-S R682G and R682G-S813Y viruses might enter cells through both TMPRSS2- or cathepsin-meditated pathways for infection and immune stimulation." (PMID 35585971, 2022). "First of all, polymorphisms and variations in the ACE2 and TMPRSS2 genes may impact SARS-COV-2 virus invasion and population susceptibility to the infection." (PMID 35193695, 2022). "We observed that in regions where ACE2 and TMPRSS2 overlap, actual infection occurs." (PMID 35255100, 2022). "Indeed, we observed a much greater increase in infection for Delta (34×) under TMPRSS2 overexpression conditions and a smaller increase (6×) for Omicron in the presence of overexpressed TMPRSS2." (PMID 35104837, 2022). "Collectively, our results suggest that Omicron variant infection is not enhanced by TMPRSS2 but is largely mediated via the endocytic pathway." (PMID 34951565, 2022). "The depletion of TMPRSS2 as well as the co-treatment of siCTSL and siTMPRSS2 could significantly abort the infection of pseudotyped SARS-CoV-2 in Calu-3 cells." (PMID 35572668, 2022). "Notably, a very distinct pattern of replicative fitness was observed in VeroE6/TMPRSS2 cells infected with the Omicron and WT viruses, which highlights the physiological relevance of the airway organoids for modeling infection." (PMID 35710786, 2022). "However, the depletion of CTSL in CTSL–/TMPRSS2+ Calu-3 cells only slightly decreased the infection of pseudotyped SARS-CoV-2 S/HIV-1 viruses." (PMID 35572668, 2022). "Treatment given at a time when viral entry and replication are high can be detrimental as the upregulation of ACE2 and TMPRSS2 may enhance infection." (PMID 36405732, 2022). "Enoxaparin enhanced AAT inhibition of both TMPRSS2 activity and infection of hAEc with HCoV-229E." (PMID 35338216, 2022). "Accordingly, efficient in vivo infection requires TMPRSS2 activity." (PMID 35562967, 2022). "Thus, the furin/TMPRSS2-dependent early entry pathway can be used almost exclusively by these viruses to achieve infection." (PMID 36243815, 2022). "Of these priming sites, the proteolytically sensitive polybasic sequence of the activation loop at the S1/S2 interface and the S2′ location within the S2 subunit of the S protein are cleaved by furin and TMPRSS2, which are important for the infection of the target cell." (PMID 36144551, 2022). "This may arise because angiotensin-converting enzyme 2 receptor and cellular protease TMPRSS2 are the SARS-CoV-2 entry requirements for infection." (PMID 36067987, 2022). "During the initiation of infection, the receptor-binding domain (RBD) of the spike protein binds to host membrane-associated angiotensin-converting enzyme 2 (ACE2), and transmembrane protease serine 2 (TMPRSS2) proteolytically cleaves and activates viral envelope glycoproteins." (PMID 35057070, 2022). "Additionally, angiotensin-converting enzyme II (ACE2), a host protein that binds to the new coronavirus, and transmembrane protease serine 2 (TMPRSS2), which promotes infection, are expressed in the oral mucosal epithelium." (PMID 35409838, 2022). "We also quantified the relative expression of BSG/CD147, ACE2 (given its involvement in SARS-CoV-2 binding and infection of many cell types), as well as cell surface protease TMPRSS2 and endosomal Cathepsin L (CTSL) in podocytes infected with SARS-CoV-2 for 72 h using different MOIs." (PMID 35517495, 2022). "Key questions are timing of the camostat intervention, i.e., we need to understand at what time point in SARS-CoV-2 infection that inhibition of TMPRSS2 might affect the direction and path of infection." (PMID 35412356, 2022).